CRP (C-reactive protein)
Diseases named in the same sentence as CRP in open-access papers (continued):
Sharing a sentence is not in itself a finding about the gene and the disease.
cognitive decline (continued). "Over an average follow-up period of 13 years, HBP and elevated glucose, CRP, homocysteine, IL-6, and ACR concentrations were significantly associated with the risk of mortality in the individuals with incident AD/ADRD or cognitive decline." (PMID 38628973, 2024). "Any future initiative aimed at pharmacologic modulation of CRP (e.g., blocking CRP-mCRP dissociation), could represent a new therapeutic approach protecting against intestinal inflammation and concomitantly reducing the risk of neuroinflammation, neurodegeneration, and cognitive decline." (PMID 38665135, 2024). "Thus, elevated CRP levels in the blood during the preoperative period among patients who develop POCD can be indicative of several underlying processes that may contribute to cognitive decline after surgery." (PMID 39596303, 2024). "While some studies have shown associations between inflammatory biomarkers like CRP, IL-6, and TNF-α with cognitive decline and neurodegenerative diseases, their utility as predictive factors remains uncertain." (PMID 38891863, 2024). "In a recent study by Tao and colleagues (2021), it was found that CRP was related to longitudinal cognitive decline as measured by Mini-Mental State Examination scores, but only in people who were homozygous for APOE4." (PMID 39358806, 2024). "Among 13 factors included in this study, HBP, elevated glucose, CRP, homocysteine, IL-6, and elevated urine ACR were significantly associated with the risk of all-cause mortality in those with incident AD/ADRD or cognitive decline." (PMID 38628973, 2024). "These decreases in plasma CRP levels, indicative of lowered peripheral inflammation, occurred in AD subjects who also showed stoppage of their cognitive decline over the same lengthy period." (PMID 37298603, 2023). "We also found a significant interaction between CRP concentration and diagnosis in predicting future cognitive decline." (PMID 37593375, 2023). "Among these patients with AD, lower baseline CRP was correlated with greater future cognitive decline (r = −0.41, p = 0.013)." (PMID 37593375, 2023). "Individuals in the elevated group of Hs-CRP change had a significantly faster cognitive decline (−0.0070 SD/year, p = 0.016) compared with those in the stable group." (PMID 37190623, 2023). "A large England cohort, conducted in middle-aged and older populations, demonstrated that individuals in the third and highest quartiles of Hs-CRP had a significantly faster cognitive decline than those in the lowest quartile." (PMID 37190623, 2023). "Since the diagnosis of cognitive decline currently hinges on various scales, medical professionals are increasingly interested in exploring biological markers such as CRP for early detection." (PMID 37509012, 2023). "In large observational cohorts, systemic inflammatory markers like C-reactive protein (CRP) were associated with both brain amyloid deposition and cognitive decline later in life." (PMID 36217192, 2022). "Hcy and other pro-inflammatory factors such as interleukin-6 (IL-6), C-reactive protein (CRP), and alpha-1-antichymotrypsin (ACT) have been linked to neuroinflammation and cognitive decline." (PMID 34200792, 2021). "Related also with the inflammatory processes, C-reactive protein (CRP) has been suggested to contribute to cognitive decline." (PMID 34072914, 2021). "Both IL‐6 and CRP have consistently been reported to be strongly correlated with various age‐related diseases and are considered valuable predictors of physical and cognitive decline." (PMID 33024560, 2020). "TNF-α and IL-6 influence the onset of frailty and cognitive decline, and CRP levels link muscle quality with cognitive function." (PMID 32257550, 2020). "Second, some circulating pro-inflammatory markers such as IL-6 and CRP will likely increase in these subjects and result in global cognitive decline and hippocampal atrophy." (PMID 33363509, 2020).
cognitive decline (continued). "Our finding is consistent with prior literature, which found a significant relationship between CRP and cognitive decline in females only." (PMID 32066726, 2020). "While some prospective studies have found higher rates of cognitive decline among individuals with higher CRP, the majority of these studies were among highly selected clinic or cohort samples of adults." (PMID 33382815, 2020). "CRP, a protein in the blood which is involved in the response to systemic inflammation, has been related to cognitive decline." (PMID 28659812, 2017). "CRP levels were also unrelated to cognitive decline in a further prospective study with a 6-year follow-up." (PMID 26060511, 2015). "Using the Modified Mini-Mental State Examination (3MS) as a measure of cognitive function, the researchers evaluated serum levels of IL-6, CRP, and TNF-α at baseline in relation to baseline cognition and risk of cognitive decline over two years." (PMID 25793613, 2015). "However, it is unknown whether CRP is causally linked to cognitive decline." (PMID 21915265, 2011). "To clarify, to determine if Hcy and CRP contribute to the motor dysfunction and cognitive decline in VP and PD patients, we examined the plasma Hcy/CRP and compared their levels in PD and VP patients." (PMID 21556377, 2011). "Longitudinal studies are needed to determine whether changes in BDNF and CRP levels over time are predictive of cognitive decline in bipolar disorder, as this would clarify temporal relationships and strengthen causal inference." (PMID 41367212, 2025). "This focus ensures that downstream sections, on pain biology, HPA feedback, BBB integrity, and therapeutic levers, cohere around a single, testable model, that being inflammation → IL-6/CRP → mCRP effector signaling → vascular–neuroimmune dysregulation → cognitive decline." (PMID 41373439, 2025). "Together, these studies support a mechanistic link between pain, reduced pain thresholds, CRP-mediated inflammation, BBB permeability, and neurodegenerative vulnerability, wherein CRP acts both as a marker and a driver of inflammation-induced cognitive decline." (PMID 41373439, 2025). "In addition to the strong association of elevated CRP levels with neurodegenerative diseases, a recent meta-analysis showed the link between cognitive decline and CRP levels." (PMID 40534869, 2025). "Beyond GA, it is possible to measure biological parameters indicating health deterioration among older cancer patients such as the levels of circulating C-reactive protein, a parameter of systemic inflammation, to predict other parameters such as cognitive decline." (PMID 38760832, 2024). "Furthermore, blood levels of C-reactive protein and IL-6 have also been shown to predict future cognitive decline." (PMID 39154864, 2024). "Furthermore, plasma IAPP-Ig levels, especially IAPP-IgA, correlated with cognitive decline, C-reactive protein, cerebrospinal fluid Aβ and tau, neurofibrillary tangles, and brain IAPP exclusively in APOE4 non-carriers." (PMID 36835187, 2023). "Several studies have also demonstrated an association between elevated levels of proinflammatory markers, including C-reactive protein, IL-6, and tumor necrosis factor-alpha (TNF-α), and cognitive decline as well as an increased risk of neurodegenerative disorders (e.g., AD and vascular dementia)." (PMID 38089627, 2023). "Plasma CRP is a nonspecific marker of the acute-phase inflammatory response, infection, and tissue damage, all of which are associated with cognitive decline." (PMID 36675728, 2022). "We hypothesized that low-grade inflammation, estimated by interleukin-6 (IL-6), tumor necrosis factor alpha (TNF-α), and high-sensitivity CRP (hs-CRP), is a predictor of cognitive decline in the general population." (PMID 36195448, 2022). "The risk of cognitive decline was highest in those with an intermediate hs-CRP level and poor CVH, but this relationship was not significant." (PMID 34293257, 2021).
cognitive decline (continued). "In the stratified analysis conducted across hs-CRP tertiles, the risk of cognitive decline was highest in the group with high hs-CRP levels and poor CVH, although this relationship was not statistically significant." (PMID 34293257, 2021). "Elevated IL-6 in midlife is associated with cognitive decline whereas increased CRP levels did not predict the concurrent cognitive decline." (PMID 32455946, 2020). "In this nationally representative, population-based sample of White and Black American adults aged ≥45 years at baseline, higher CRP was associated with worse memory and verbal fluency at baseline but not with rate of cognitive decline over a span of 12 years." (PMID 33382815, 2020). "We did not demonstrate an association between CRP and cognitive decline in this population, apart from the baseline association with working memory performance where the association was borderline significant." (PMID 29338747, 2018). "Similarly, subjects with MetS and high C-reactive protein suffered greater cognitive decline in the follow-up than controls and subjects with MetS without high inflammation markers." (PMID 29579115, 2018). "Increased CRP, a marker of increased systemic inflammation, may occur later in the evolution of cognitive decline with aging and in neurodegeneration." (PMID 29338747, 2018). "Across the Atlantic, the Health, Aging, and Body Composition study found that being in the highest tertile of CRP levels at baseline had the same odds as being in the lower tertiles when predicting 4 years cognitive decline in change-scores longitudinal design." (PMID 27239544, 2016). "In the group without an e4 allele, log(CRP) was associated with a decreased risk of longitudinal cognitive decline (OR: 0.57, 95% CI: 0.33–0.96, P = 0.04)." (PMID 24305621, 2014). "Serum CRP is regarded as an independent risk factor for cardiovascular disease, and previous studies also suggested a relationship to cognitive decline, although no definitive mechanism has been established." (PMID 23978069, 2013). "Taken together, these data currently do not support a role for CRP in cognitive decline, either directly causal or indirectly as a causative factor in vascular disease, but further study is necessary to draw definitive conclusions." (PMID 21915265, 2011). "During follow-up higher concentrations of CRP associated with an increased rate of cognitive decline measured only with the immediate PLT (P = 0.016), but not in the other cognitive tests." (PMID 21915265, 2011). "Additionally, ACEs may contribute to cognitive decline indirectly through depressive symptoms and chronic inflammation, reflected by elevated levels of interleukin-6 and C-reactive protein in adulthood." (PMID 40674657, 2025). "We observed a significant interaction between diagnosis and CRP concentration in predicting the annual cognitive changes; post hoc analysis revealed that among these patients diagnosed with AD, lower baseline hs-CRP was correlated with greater future cognitive decline." (PMID 37593375, 2023). "However, in a longitudinal cohort, the APOE haplotype, but not the CRP haplotype, was associated with life-long cognitive decline, thus disproving any association between CRP and cognitive decline." (PMID 37445986, 2023). "Fibrinogen and CRP are acute-phase proteins that are used as non-specific markers for inflammatory disease, and both were shown to be associated with cognitive decline in previous studies." (PMID 35493931, 2022). "However, APOE but not CRP haplotype was associated with life-long cognitive decline in a longitudinal cohort, which does not support a causal effect of CRP on cognitive decline." (PMID 36348357, 2022). "We hypothesized that higher baseline CRP concentration would be associated with worse cognitive functioning at baseline and a steeper rate of cognitive decline over time, independent of other risk factors." (PMID 33382815, 2020).
cognitive decline (continued). "Neither serum CRP nor the DNAm CRP score were found to associate with longitudinal change in cognitive ability over time indicating no predictive relationship between either measure of inflammation and cognitive decline." (PMID 32718350, 2020). "We found that higher CRP was associated with worse memory (B = -.039, 95% CI [-.065,-.014]) and verbal fluency at baseline (B = -.195, 95% CI [-.219,-.170]), but not with rate of cognitive decline." (PMID 33382815, 2020). "APOE ɛ4 is also associated with altered levels of C-reactive protein, a systemic marker of inflammation which has been found to be associated with frailty, memory performance and lower medial temporal volume, and cognitive decline in a non-demented population." (PMID 31221191, 2019). "Likewise, CRP is predictive of later cognitive decline in mid-life." (PMID 30555318, 2018). "None of the other OS markers or CRP were linked to cognitive decline over 4 years." (PMID 29338747, 2018). "Interestingly, (IL)-6 and hs-CRP are predictors used for cognitive decline." (PMID 29088788, 2017). "In the ET2DS, higher levels of fibrinogen, TNF-α, and IL-6 but not CRP were associated with lower measures of cognitive function; higher baseline levels of fibrinogen and IL-6 additionally predicted a steeper 4-year cognitive decline." (PMID 26060511, 2015). "However, although some epidemiological studies indeed suggest an association of high concentrations of CRP with risk of dementia or cognitive decline, the data are not consistent." (PMID 21915265, 2011). "If CRP itself is not directly causal in cognitive decline, concentrations of CRP may be the read-out of mechanisms that causes cognitive decline." (PMID 21915265, 2011). "This suggests that while elevated circulating CRP may be involved in the physiological processes associated with poorer cognition, even the high-sensitivity assay may not be clinically suitable as a marker for cognitive decline." (PMID 39807297, 2025). "Studies have shown that an increase in peripheral pro-inflammatory markers such as C-reactive protein (CRP), Interleukin-6 (IL-6) and soluble CD40 ligand (sCD40L) accompanies cognitive decline." (PMID 37686198, 2023). "Specifically, higher inflammation levels correspond to elevated levels of interleukin-6 (IL-6) and C-reactive protein (CRP), leading to an accelerated rate of cognitive decline." (PMID 38075216, 2023). "The negative correlations between cognitive tests (LM-A) and inflammatory factors (CRP and SII) in our results revealed the effects of cytokine storms on long-term cognitive decline." (PMID 36632218, 2023). "Inflammatory cytokines, including IL-6, IL-10, CRP, MCP-1, ICAM-1, and TNF-α, play an important role in the development of poststroke cognitive decline." (PMID 35111122, 2021). "A longitudinal study of cognitive decline in older adults used a panel of 8 blood-based markers, including APOE, plasma amyloid β 42/40 ratio, telomere length, serum glucose, cystatin C, C-reactive protein (CRP), interleukin-6 (IL-6), and albumin." (PMID 33946285, 2021). "Corroborating the inflammation in PD and its detrimental role, increase in the C-reactive protein (CRP), an acute phase protein, can predict cognitive decline PD prognosis and correlated to severe motor symptoms in PD patients." (PMID 33555429, 2021). "High levels of IL-1, IL-6, CRP, and TNF-α were also found to be potentially predictive markers for the development of Alzheimer's disease (AD) or cognitive decline." (PMID 32257550, 2020). "As people age, proinflammatory markers such as C-reactive protein (CRP), interleukin (IL)-6 and -1 beta, and tumor necrosis factor alpha (TNF-alpha) increase and are related to cognitive decline." (PMID 32509348, 2020). "High CRP, low albumin and high ESR each had a specific link to cognitive decline for specific groups within this urban adult population." (PMID 30356710, 2018).
cognitive decline (continued). "Further, peripheral CRP is a surrogate marker but not causative inflammatory mediator, thus we cannot exclude the possibility that decreased serum levels of glutathione are mirrored by simultaneous increased levels of inflammatory mediators in the CNS which in turn are linked to cognitive decline." (PMID 29338747, 2018). "We examined the clinical value of two serum markers of low-grade inflammation, C-reactive protein (CRP) and receptor of advanced glycation products (RAGE), as prognostic indices for cognitive decline." (PMID 23978069, 2013). "Whether CRP directly causes cognitive decline in the brain is not well examined." (PMID 21915265, 2011). "Conversely, the relationship between elevated CRP levels and poorer cognitive performance, particularly in the GIC group, underscores the potential role of systemic inflammation in the pathophysiology of cognitive decline in bipolar disorder." (PMID 41367212, 2025). "In addition, increased levels of inflammatory markers like IL-1β, IL-12, TNF-α, CRP, low CSF and serum BDNF, and altered adipokines are observed in individuals exhibiting both cognitive decline and depressive symptoms." (PMID 40807098, 2025). "Meta-analyses were used to longitudinally compare the baseline concentration of CRP in the blood of acute stroke patients with cognitive decline and without cognitive decline." (PMID 37509012, 2023). "Furthermore, compared to the other patients, those with cognitive decline had a higher median (IQR) BMI (p = 0.032), a higher average CRP (p = 0.002), and a higher average JADAS27 (p = 0.048); fewer of these patients were receiving biologics (p = 0.016)." (PMID 35885032, 2022). "Baseline TNF-α did not predict cognitive decline, and hs-CRP did not predict cognitive performance or decline after 10-years." (PMID 36195448, 2022). "Since a comparatively high consumption of fruits and vegetables could contribute to a delay in cognitive decline, the effects of CVH and hs-CRP could be masked." (PMID 34293257, 2021). "CRP is a marker of a nonspecific acute-phase response in inflammation, infection, and tissue damage, correlated with cognitive decline." (PMID 29641605, 2018). "Serum CRP, RAGE, and left hippocampal myo-inositol may provide prognostic information on cognitive decline." (PMID 23978069, 2013). "Evidence suggests that in the ageing brain, the microglial macrophages may become chronically activated, leading to the prolonged production of pro-inflammatory cytokines (e.g. IL-6; TNF-α) and proteins such as C-reactive protein (CRP), which are well-established predictors of cognitive decline." (PMID 40370669, 2025). "Interestingly, advancing age correlated with elevated CRP only among non-depressed participants, suggesting a complex and heterogeneous relationship between inflammation, cognitive decline, demographic variables, and affective symptoms in aging populations." (PMID 40943152, 2025). "Elevated IL-6 but not CRP in midlife prospectively predicts cognitive decline, evidenced by MMSE." (PMID 36334250, 2023). "Through a meta-analysis of 3893 subjects, we observed that peripheral CRP levels could be significantly elevated in patients with cognitive decline (CD) compared to those in patients without CD." (PMID 37509012, 2023). "The idea that the normal IgA response is disturbed in APOEε4 carriers was further highlighted by the found correlations after analysis of cohort I. Here, plasma IgA levels correlated significantly with CRP, Aβ pathology, and cognitive decline exclusively in APOEε4 non-carriers." (PMID 36008818, 2022). "The inflammatory marker of CRP (C-Reactive Protein) may not account for accelerated cognitive decline during the COVID-19 pandemic." (PMID 36078381, 2022). "While the association of CRP on baseline cognition was robust, our hypothesis that elevated CRP would increase rate of cognitive decline was not supported." (PMID 33382815, 2020).